ALB (albumin)
Diseases named in the same sentence as ALB in open-access papers (continued):
Sharing a sentence is not in itself a finding about the gene and the disease.
Sepsis (continued). "It further elucidates the strong association between the patterns of serum albumin level changes post-treatment in sepsis patients and their prognoses, offering crucial insights for clinicians in devising targeted treatment strategies." (PMID 39101009, 2024). "Low levels of albumin are prevalent among patients with severe sepsis and are associated with more severe inflammation." (PMID 39135753, 2024). "Patient-specific factors independently associated with the necessity for intubation were low albumin and being of younger age, the only pneumonia-specific factor was sepsis." (PMID 38525765, 2024). "Previous research demonstrates that diminished serum albumin as a risk factor for death in patients with prolonged sepsis, and that hospitalized patients with reduced albumin levels have higher mortality rates." (PMID 38510084, 2024). "The summaryof the analysis results highlighted that an elevatedlactate/albumin ratio is associated with higher mortalityin sepsis patients (OR=2.16, 95% CI: 1.58 to2.95, I2=76.2%)." (PMID 39139159, 2024). "Conditions leading to low serum albumin, such as inflammation, liver disease, sepsis, burns, and any cause of critical illness, are often associated with a corresponding fall in plasma zinc levels." (PMID 38975455, 2024). "Our study findings showed a significant association between decreased levels of albumin and poor prognosis in sepsis." (PMID 38826606, 2024). "Temperature, PaO2 levels, and serum ALB concentration were independent risk factors for sepsis in children with IPD." (PMID 38898407, 2024). "Low serum albumin levels are associated with increased mortality in acute illness, including sepsis." (PMID 39459557, 2024). "Clinicians should consider serum albumin levels in conjunction with other diagnostic tools to assess sepsis severity." (PMID 39539863, 2024). "In cases of sepsis, individuals are prone to exhibit reduced levels of serum albumin, and this is strongly linked to an unfavorable prognosis." (PMID 38826606, 2024). "Temperature (OR 3.80, 95% CI 1.62–8.87; P = 0.0021), PaO2 (OR 0.99, 95% CI 0.98-1.00; P = 0.0266), and albumin (OR 0.89, 95% CI 0.80–0.99; P = 0.0329) were found to be independent risk factors for sepsis in children with IPD." (PMID 38898407, 2024). "Previous evidence suggests that decreased serum albumin is associated with higher mortality in sepsis and AKI cohorts." (PMID 38898431, 2024). "Recently, the LAR (LDH/ALB ratio) has been found to be significantly correlated with the mortality rates of sepsis and sepsis-associated acute kidney injury." (PMID 38962086, 2024). "A recent meta-analysis pointed that among sepsis and surgical patients, balanced crystalloid and albumin attained lower mortality rates and lower risk of acute kidney injury than saline and low molecular weight hydroxyethyl starch." (PMID 38194181, 2024). "A low serum albumin level is a risk factor for anastomotic leakage and is a risk factor for mortality during sepsis due to vascular hyperpermeability." (PMID 38756300, 2024). "Higher albumin levels have been reported to be associated with a lower risk of delirium in patients with sepsis, which supports our conclusion." (PMID 39135753, 2024). "C-reactive protein/serum albumin ratio and the quick Pitt bacteremia score are two useful tools for clinicians to assess severity and predict mortality risk in patients with sepsis attributable to bloodstream infections." (PMID 39252713, 2024). "The aim of this study was to explore the association between lactate/albumin ratio and the prognosis of sepsis patients." (PMID 39139159, 2024). "A plethora of clinical studies have demonstrated that low levels of albumin are linked to increased mortality risk in conditions including sepsis, septic shock, and heart failure." (PMID 37790597, 2023). "Experts recommend using albumin in the hemodynamic management of ARDS patients, especially for cases with sepsis-associated ARDS or low serum albumin." (PMID 37089426, 2023).
Sepsis (continued). "HSA regulates the blood osmotic pressure and improves edema, hypoalbuminemia, glycocalyx degradation and hypovolemia caused by sepsis." (PMID 37629199, 2023). "Two observational studies found serum albumin to be a risk factor for death in patients with sepsis." (PMID 37365506, 2023). "According to the study, low serum albumin levels are associated with an increased risk of death in patients with severe sepsis." (PMID 37366985, 2023). "Acute and chronic reduced levels of serum albumin have both been freely linked to a higher risk of mortality in sepsis." (PMID 37123772, 2023). "Given the safety concerns observed in cirrhosis, such as pulmonary edema and hypervolemia associated with albumin therapy, cautious integration of albumin into sepsis treatment is mandatory." (PMID 38139434, 2023). "Slow return of albumin-rich lymph is the likely cause of maldistribution of albumin during inflammatory conditions, as the synthetic rate of albumin is normal during major abdominal surgery and sepsis." (PMID 37245039, 2023). "Albumin and bilirubin levels have been reported to be associated with mortality among sepsis patients in previous studies." (PMID 38239259, 2023). "Albumin kinetics in patients critically ill with COVID-19 compared with patients critically ill with sepsis or other causes have recently been studied." (PMID 37810906, 2023). "PCAS itself increases vascular permeability as a result of sepsis-like mechanism and consequently leads to the loss of serum ALB." (PMID 37510683, 2023). "Albumin responds to systemic inflammation and nutritional status, and some studies have found an association between albumin levels and poor prognosis in sepsis and acute kidney injury (AKI)." (PMID 37194715, 2023). "It is now accepted that a low albumin level is associated with higher mortality in patients with sepsis." (PMID 37072768, 2023). "In individuals who develop catastrophic sepsis and organ failure, critical stage low blood albumin is connected to an increased risk of severity and death." (PMID 37123772, 2023). "The Fluid Expansion as Supportive Therapy (FEAST) study, conducted in Africa, found an increased risk of death among children with sepsis who received early treatment with bolus 5% albumin or 0.9% saline, in comparison with the control group." (PMID 37374251, 2023). "The association between low albumin-levels (≤3.1 g/dL) and poor outcomes, including longer time of mechanical ventilation and vasopressors in sepsis patients, has been reported earlier." (PMID 36828485, 2023). "The albumin (ALB) level is a common laboratory indicator that is negatively associated with mortality in patients with sepsis." (PMID 35109818, 2022). "It is well-known that hypoproteinemia is a widespread clinical complication in patients with sepsis, and that the ALB level is an early predictor for mortality risk among such patients." (PMID 35109818, 2022). "Patients with sepsis have different degrees of ALB synthesis deficiencies because nutrients cannot be consumed and used efficiently in the liver." (PMID 35109818, 2022). "Lasso regression showed postoperative sepsis was associated with gender (female), pre-operative fever, serum albumin (<35 g/L), positive urine culture, serum WBC (≥10,000 cells/ml), serum neutrophil, positive urine nitrite and operation type (fURS)." (PMID 35495750, 2022). "Serum albumin concentration reflects the host nutritional and inflammatory status and is associated with the prognosis of patients with sepsis." (PMID 36494633, 2022). "Critically ill patients with sepsis suffer damage to endothelial cells and glycocalyx (endotheliopathy), which causes the breakdown of tight junctions with extravascular leakage of albumin or AT." (PMID 36248813, 2022). "One study clarified that low serum albumin levels (< 29.2 g/L) was an independent risk factor for 28-day mortality in sepsis." (PMID 36528689, 2022).
Sepsis (continued). "An elevated C‐reactive protein/albumin ratio (CRP/ALB) 72 h after admission indicates an increased risk of mortality in patients with sepsis." (PMID 35182022, 2022). "Lastly, in patients with sepsis, albumin oxidation levels are inversely associated with 90-day mortality rate, independent of shock or sepsis treatment and a higher pool of reduced albumin correlated with a lower SOFA score at dayseven." (PMID 35624664, 2022). "Although both RDW and albumin are associated with sepsis prognosis and reflect a systemic inflammatory response, they show opposite responses in terms of inflammation." (PMID 36211519, 2022). "This study revealed that ALB levels were lower in the sepsis group than in the non-sepsis group, and logistic regression demonstrated that decreased albumin level is associated with increased risk for sepsis." (PMID 36189371, 2022). "Our study found that albumin and lactate are independent risk factors for predicting a poor prognosis due to sepsis in AP patients in the ICU, and this is consistent with previous studies." (PMID 35685488, 2022). "The 28-day all-cause mortality improved after albumin administration in patients with sepsis and CHD." (PMID 36337861, 2022). "Low birth weight and low serum albumin levels are associated with an increased development of respiratory distress in early onset of sepsis in infants." (PMID 36245714, 2022). "Lactic acid, renal insufficiency, thrombocytopenia, lung infection, and high fever are considered risk factors for poor sepsis outcomes, while plasma albumin and plasma IgG levels can be protective factors." (PMID 34991569, 2022). "In critically ill patients with cirrhosis and sepsis-induced hypotension 20% albumin restores arterial pressure more quickly but causes more pulmonary complications than plasmalyte." (PMID 36300192, 2022). "In patients with severe sepsis, lower albumin level has been linked with poor clinical outcomes and was an independent predictor of prognosis in patients with sepsis and septic shock, according to several studies." (PMID 36577937, 2022). "Accumulating evidence has shown that serum albumin level is closely associated with inflammation and nutrition and is significantly associated with prognosis in patients with sepsis." (PMID 35990041, 2022). "In inflammatory bowel disease with chronic inflammation, surgical stress increases the risk of postoperative sepsis if preoperative serum albumin levels are low." (PMID 33925831, 2021). "Arterial lactate/albumin ratio, combined index, is associated with mortality in critically ill patients with sepsis or septic shock, in some studies." (PMID 34943582, 2021). "The objective of this study was to investigate the association of timing of albumin combined with 28-day mortality in patients with sepsis." (PMID 33689042, 2021). "The ALBIOS trial showed that in patients with severe sepsis the use of 20% albumin to maintain serum albumin above 3 g/dl was associated with higher mean arterial pressure and less FO; moreover, the septic shock subgroup showed a survival benefit." (PMID 33710670, 2021). "Albumin can modulate innate immune responses to sepsis and cirrhosis-associated prostaglandin E2-mediated immune dysfunction following albumin infusion." (PMID 34571946, 2021). "In sepsis, acute and chronic states of low serum albumin are independently associated with increased risk of mortality." (PMID 33925831, 2021). "Low albumin level also causes altered protein binding of antimicrobials, especially in sepsis patients, with increased volume of distribution." (PMID 34917416, 2021). "Sepsis is a common cause of mortality in ICUs, and low serum albumin levels in the acute phase are associated with increased risks of severity and death in patients who develop severe sepsis and organ failure." (PMID 33925831, 2021).
Sepsis (continued). "We found that lnc‐MALAT1/miR‐125a axis was positively associated with APACHE II score, SOFA score, Scr, CRP, TNF‐α, IL‐1β, IL‐6, and IL‐8, while negatively associated with albumin in sepsis patients." (PMID 32309886, 2020). "Clinically, we found a phenomenon in which the high neutrophil percentage and the low albumin levels are associated with poor outcomes in patients with severe sepsis or septic shock." (PMID 32238212, 2020). "A recent study reported a predictive model that included three factors (TSB, bilirubin/albumin ratio, and sepsis) in the risk assessment of ABE, but further clinical validation is needed." (PMID 33329342, 2020). "This study found that iso-oncotic albumin was associated with better survival benefit in sepsis patients who suffer hypovolemia due to extravascular fluid loss caused by increased vascular permeability." (PMID 33317590, 2020). "In this study, we investigated the association between albumin-adjusted plasma-free thiol levels in relation to (sepsis-associated) AKI in critically ill patients as a biomarker for oxidative stress." (PMID 33207555, 2020). "Multiple studies suggest that there is a continuous association between lower serum albumin and higher mortality in patients with cancer, trauma and recent surgery, myocardial infarction (MI), heart failure, stroke and sepsis." (PMID 32776978, 2020). "The importance of maintaining albumin level in burn injury is essential for wound healing, decreasing the susceptibility of sepsis, and preventing acute respiratory distress syndrome, the leading causes of death in burn injuries." (PMID 32140223, 2020). "In sepsis patients, balanced crystalloids and iso-oncotic albumin were associated with lower mortality rates, lower risks of acute kidney injury, and less red blood cell transfusion volume." (PMID 33317590, 2020). "The last coefficient (0.83SEPSIS) accounts for the mean fall in BChE-A associated with the presence of sepsis, for any given albumin and cholesterol level." (PMID 31178662, 2019). "It was not inferior to other laboratory values, including activated partial thromboplastin time (AUC: 0.729), C‐reactive protein (AUC: 0.727), albumin (AUC: 0.834), prothrombin time (AUC: 0.816), and creatinine (AUC: 0.837) known to be associated with sepsis." (PMID 30985959, 2019). "In a single-site prospective cohort study carried out in a medical-surgical ICU of a tertiary care center, APACHE II score and albumin level were independent risk factors for mortality in ICU patients with severe sepsis or septic shock." (PMID 30297655, 2018). "These previous studies have reported that the CRP/ALB ratio measured on admission was an independent risk factor in patients with severe sepsis or septic shock." (PMID 29495423, 2018). "We did find an association between U-NGAL day 3 and both urine albumin and FENa also when adjusting for gender, gestational age, and sepsis." (PMID 28068947, 2017). "Several reports showed that serum albumin levels were associated with prognosis in pneumonia, severe sepsis, and bacteremia." (PMID 28938875, 2017). "The lactate/albumin ratio has been reported to be associated with mortality in pediatric patients with sepsis." (PMID 28869492, 2017). "PDA and PDA size was associated with urine albumin also when adjusted for gestational age, gender, and sepsis." (PMID 28068947, 2017). "On regression we found PDA and PDA size to be associated with urine albumin also when adjusted for adjusting for gender, gestational age, and sepsis." (PMID 28068947, 2017). "In our study, 6 variables (BNP, albumin, total bilirubin, D-dimer, lactate levels, and mechanical ventilation in 24 hours) were included in the final Mortality Risk Model for Pediatric Sepsis (MRMFPS)." (PMID 28514310, 2017). "Among factors that can affect drug pharmacokinetics during the early phases of sepsis, urinary loss of both free and albumin–bound antimicrobials should be considered." (PMID 27846855, 2016).
Sepsis (continued). "Serum A-FABP concentrations were positively associated with serum creatinine and albumin and predict a worse hospital outcome in critically ill patients with sepsis." (PMID 28042581, 2016). "A very recent study indicates that combined albumin/terlipressin treatment appears to be safe and effective in patients presenting with acute hepatorenal syndrome associated with sepsis, further supporting early administration of this treatment." (PMID 25983746, 2015). "Recent studies also demonstrated that endothelial cell death is associated with pulmonary microvascular albumin leak in sepsis." (PMID 26394396, 2015). "Degradation of glycocalyx will expose the endothelial cells to oxidative damage, which has been linked to increased porosity, and interstitial loss of albumin observed in both severe sepsis and chronic conditions like diabetes or hypertension." (PMID 25887223, 2015). "In 2011, a large meta-analysis which included 17 studies demonstrated that albumin use in patients with sepsis was associated with a decrease in mortality." (PMID 25474401, 2014). "A subsequent meta-analysis that included 17 RCTs comparing albumin solutions with other fluids for fluid resuscitation in patients with sepsis reported that albumin use was associated with decreased mortality (odds ratio, 0.82; 95% CI, 0.67 to 1.0; P = 0.047)." (PMID 25042164, 2014). "The OR for IVIG/IVIGAM vs. albumin was estimated at 0.75 (with a 95% CrI of 0.58 to 0.96) indicating a reduction in the odds of all-cause mortality for patients with severe sepsis compared with albumin." (PMID 25434816, 2014). "Serum albumin is strongly associated with the severity and outcome of sepsis in critically ill patients and is in keeping with our findings." (PMID 24350088, 2013). "A meta-analysis suggested that fluid resuscitation with albumin compared to crystalloids was associated with improved survival in patients with severe sepsis." (PMID 23601847, 2013). "In a recent study performed in rats with polymicrobial sepsis, treatment with hyperoncotic albumin attenuates hepatic injury in association with reduced plasma levels of IL-1β, IL-6, liver enzymes, and O2- concentrations." (PMID 23548047, 2013). "Low levels of albumin and total cholesterol, common in older patients, are other surrogate markers for susceptibility to increased sepsis and mortality." (PMID 23742036, 2013). "A low preoperative albumin concentration (<25 g/L) was related to increased postoperative mortality, and sepsis was the main cause of death." (PMID 22669399, 2012). "Albumin remained an independent risk of lower 30-day survival when stratifying for trauma (n = 254) or severe sepsis (n = 765)." (PMID 16356223, 2005). "The study aimed to assess whether serum albumin trajectories in sepsis are associated with fluid exposure, modulated by early norepinephrine therapy, and related to 30-day mortality." (PMID 42122937, 2026). "Use of albumin decreased the risk of sepsis‐associated delirium." (PMID 41522719, 2026). "However, a post hoc analysis focusing specifically on patients with severe sepsis revealed that albumin therapy was associated with a reduced odds ratio of death, suggesting a potential benefit in this subgroup of patients." (PMID 40699702, 2025). "After adjusting cardiogenic shock, respiratory failure, SAPSII, SOFA, GCS, CCI, SPO2, platelet, total bilirubin, vasopressor, antibiotics, and insulin, albumin infusion was associated with decreased risk of sepsis in the AP patients (Model 2: adjusted OR=0.37, 95%CI = 0.13–0.88, P = 0.039)." (PMID 40773463, 2025). "Finally, although the PIICS criteria of lymphopenia, albumin, and length of stay were all significant in their association with the development of sepsis, lymphopenia had the strongest association." (PMID 40555121, 2025).